IFNL1 (interferon lambda 1)
Description:
Cytokine with antiviral, antitumour and immunomodulatory activities. Plays a critical role in the antiviral host defense, predominantly in the epithelial tissues. Acts as a ligand for the heterodimeric class II cytokine receptor composed of IL10RB and IFNLR1, and receptor engagement leads to the activation of the JAK/STAT signaling pathway resulting in the expression of IFN-stimulated genes (ISG), which mediate the antiviral state. Has a restricted receptor distribution and therefore restricted targets: is primarily active in epithelial cells and this cell type-selective action is because of the epithelial cell-specific expression of its receptor IFNLR1. Exerts an immunomodulatory effect by up-regulating MHC class I antigen expression.
Synonyms: IL-29; IL29
Tractability: Antibody: its Gene Ontology location is reachable by antibodies, with high confidence; UniProt places it where antibodies can reach, with medium confidence; UniProt predicts a signal peptide or a membrane-spanning region.
Gene: Protein-coding gene on chromosome 19 (39,296,407 to 39,298,673, forward strand). Ensembl gene ENSG00000182393.
Subcellular location: Secreted
Pathways (Reactome):
Immune System: Interleukin-20 family signaling; Other interleukin signaling
Gene Ontology:
Molecular function: interleukin-28 receptor binding; signaling receptor binding; cytokine activity
Biological process: defense response to virus; negative regulation of cell population proliferation; negative regulation of DNA-templated transcription; negative regulation of interleukin-13 production; negative regulation of interleukin-5 production; negative regulation of memory T cell differentiation; negative regulation of T cell differentiation; negative regulation of type 2 immune response; positive regulation of DNA-templated transcription; positive regulation of MHC class I biosynthetic process; positive regulation of receptor signaling pathway via JAK-STAT; positive regulation of type II interferon production; positive regulation of tyrosine phosphorylation of STAT protein; cellular response to virus; innate immune response; positive regulation of immune response; type III interferon-mediated signaling pathway; cell surface receptor signaling pathway via JAK-STAT
Cellular component: extracellular region; interleukin-28 receptor complex
Genetic constraint (gnomAD): Loss-of-function variants: 16 observed, 18.24 expected, observed/expected ratio (o/e) 0.88, 90% interval 0.59 to 1.33. The upper end of that interval is the gene's LOEUF score, 1.33, which puts it in group 5 of 6, group 1 being the genes least tolerant of losing a copy. Missense variants: 262 observed, 261.34 expected, observed/expected ratio (o/e) 1, 90% interval 0.9 to 1.11. Synonymous variants: 104 observed, 118.17 expected, observed/expected ratio (o/e) 0.88, 90% interval 0.75 to 1.04.
Homologues: Orthologues: chimpanzee IFNL1 (98% identical), macaque IFNL1 (92% identical), dog IFNL1 (70% identical), dog IL29L (69% identical), pig IL29 (68% identical), tropical clawed frog ifnl3 (23% identical), tropical clawed frog ifnl2 (21% identical), tropical clawed frog ifnl3.4 (21% identical). Paralogues in human: IFNL3 (70% identical), IFNL2 (70% identical).
Diseases named in the same sentence as IFNL1 in open-access papers:
IFNL1 is named in the same sentence as 92 diseases in open-access papers, as found by Europe PMC text mining. Sharing a sentence is not in itself a finding about the gene and the disease. The quoted sentences say what the papers report.
viral infection (36 papers, 2010 to 2025). "Based on all evidence, the uses of IFNLs as drugs against viral infection has been proposed in COVID-19 patients or in individuals at high risk for infection, and current randomized clinical trials are designed with peg-IFNL1 in the case of acute COVID-19." (PMID 34775984, 2021). "This was consistent with our observations in primary cells, where pretreatment with IFNL1 blunted the inflammatory response by limiting viral infection." (PMID 34899695, 2021). "IFNL1 encodes for interferon lambda (IFN-λ, also known as IL-29), which is produced in response to viral infections by myeloid cells." (PMID 31832069, 2019). "Given the importance of the IFN response in the control of viral infections, IFN (IFNL1 and IFNL4) targeted therapies for COVID-19 are currently being developed." (PMID 38143441, 2023). "According to previous results, overexpression of RIG-I induced the expression of IFNL1 (~ 20, 000-fold) in the absence of any viral infection." (PMID 37187533, 2023).
COVID-19 (22 papers, 2020 to 2025). A disease caused by infection with severe acute respiratory syndrome coronavirus 2. "Finally, we investigated if IFNL1 or IFNL2 levels were associated with disease severity in COVID-19 patients using good (WHO 1–2), mild (WHO 3–4), and bad (WHO 5–8) clinical outcomes to stratify the large cohort of Irish patients (n = 399)." (PMID 38953458, 2024). "Indeed, we found qualitative and quantitative differences in terms of frequency of induction, amount of cytokine produced and associations with severe COVID-19 outcome among IFNL1, IFNL2, and IFNL3." (PMID 38953458, 2024). "IFNL3 was induced in 95% of COVID-19 patients and at higher median levels compared to the IFNL1 or IFNL2." (PMID 38953458, 2024). "In the overall cohort, however, only 65% of Irish COVID-19 patients had measurable IFNL1 cytokine, and the median level of IFNL1 was relatively low at 30 pg/ml." (PMID 38953458, 2024). "Another duo of a ligand and its receptor that was upregulated in plasma of severe COVID-19 is IFNL1 (INF lambda 1, type-III INF) and one of its receptors, IFNLR1." (PMID 35177642, 2022). "Stratification of 138 COVID-19 patients without any detectable IFNL1 into groups based on disease severity demonstrated a clear association between absence of IFNL1 and worse outcome." (PMID 38953458, 2024). "Moreover, we found that pregnancies with COVID-19 developed more pronounced inflammatory responses with activation of the IFNL1/IFNLR1 axis, which may trigger perinatal immune activation." (PMID 38267411, 2024). "While only IFNL3 had significantly higher levels of cytokine compared to HCV + patients, both IFNL1 and IFNL2 were significantly higher in COVID-19 patients compared to healthy controls." (PMID 38953458, 2024). "Our previous study showed a general decreased expression of IFNL1-3, IFN-I, and ISGs-mRNAs in critically ill patients with COVID-19 that required invasive mechanical ventilation." (PMID 35208821, 2022). "Both IFNL1 and IFNL2 levels were consistently low in patients with most severe COVID-19 (WHO 5–8)." (PMID 38953458, 2024). "It was striking to note that a complete absence of either IFNL1 or IFNL2 occurred more frequently with more severe COVID-19." (PMID 38953458, 2024). "In this study, we measured all three IFNL1, IFNL2, and IFNL3 cytokines in plasma from a well characterized, large COVID-19 cohort (n = 399) that included good representation from patients with a more indolent disease progression, and hence a beneficial immune response." (PMID 38953458, 2024). "This exercise revealed that, whereas the DS IFN score tracks preferentially with IFNG and IFNL1 in DS, this same ISG signature correlates significantly with eight different IFNs in COVID-19, five of which are type I IFNs (i.e., IFNA2, IFNA7/17/21, IFNA1, IFNA4/16, and IFNA10)." (PMID 37379383, 2023). "Indeed, of the 20 patients in the cohort who died of COVID-19, 12 had no detectable IFNL1 (60%) compared to the overall cohort (35%)." (PMID 38953458, 2024). "We did not detect changes in IFNL2,3, IFNL1, and IFNB1 expression, in agreement with reports of low IFN induction by SARS-CoV-2 infection and the role of several SARS-CoV-2 proteins as IFN-antagonists to limit antiviral response." (PMID 34446714, 2021). "Performing a similar analysis on the 75 COVID-19 patients with no plasma IFNL2 detectable, there was a clear association between worse outcome and absence of IFNL2 with 11 of the 20 patients who died (55%) having no detectable IFNL1 compared to 25% of the overall cohort." (PMID 38953458, 2024).
psoriasis (10 papers, 2018 to 2025). An autoimmune condition characterized by red, well-delineated plaques with silvery scales that are usually on the extensor surfaces and scalp. "IFNL1 was recently reported to be involved in the expression and production of all IFN-λ44, and might be effective in the pathogenesis of psoriasis by regulating the biological potential of IFN-λ signaling." (PMID 39009607, 2024).
influenza (9 papers, 2011 to 2025). An acute viral infection of the respiratory tract, occurring in isolated cases, in epidemics, or in pandemics; it is caused by serologically different strains of viruses (influenzaviruses) designated A, B, and C, has a 3-day incubation period, and usually lasts for 3 to 10 days. "Pretreatment of both HAMs and differentiated human monocytes with IFNL1 significantly inhibited influenza infection." (PMID 34899695, 2021). "To examine the inhibition of influenza infection in HAMs, we pre-treated with IFNL1 and IFNβ for 8 or 24 hours prior to influenza infection for 24 hours." (PMID 34899695, 2021). "We pre-treated macrophages with IFNL1 for 24h prior to infection with influenza PR8 and assayed mRNA copy number of the two viral replication-dependent mRNAs (M and NS gene)." (PMID 34899695, 2021). "In human cell culture, IFNL2, IFNL3, and the human-specific IFNλ isoform, IFNL1, are robustly induced after influenza infection, predicting the transcription of interferon-stimulated genes (ISGs)." (PMID 34899695, 2021). "Despite of reports of a redundant role of type I and III IFNs, type III IFNs are the predominant IFNs induced by influenza in the lung of mice and IFNL1 is required to control infections by mucosal pathogens in humans." (PMID 26336095, 2015). "We next assessed expression levels of various cytokines and chemokines (i.e., IFNB1, IFNL1, IFNL2/3, IFIT1, IFIT3, OAS1, MX1, IL‐6, CXCL10, and IFITM1) which were triggered by influenza and OC43 virus infections alone or together by qPCR." (PMID 38556468, 2024). "Noteworthy, syncytin-1 has been shown to weaken the antiviral response against Influenza, leading to reduced production of IFNA1, IFNL1, and IFN-γ and inducing IL10 release by peripheral monocytes (PBMCs)." (PMID 39273061, 2024).
rheumatoid arthritis (9 papers, 2012 to 2022). A chronic, systemic autoimmune disorder characterized by inflammation in the synovial membranes and articular surfaces. "IFNL protein levels are upregulated in the sera of patients with rheumatoid arthritis compared with healthy controls; more specifically IFNL1 and IFNL2 levels are upregulated in patients with active disease." (PMID 34899712, 2021).
asthma (7 papers, 2015 to 2023). "Another study demonstrated that adults with asthma had increased levels of IFNL1 compared with healthy controls and that these elevated IFNL1 levels correlated with presence of neutrophilia in the sputum." (PMID 34899712, 2021). "Additionally, adenovirus mediated expression of human IFNL1 in a murine asthma model led to attenuated eosinophilia, diminished antigen specific Th2 responses, and promotion of regulatory T (Treg) responses." (PMID 34899712, 2021). "At baseline, both children and adults with asthma have increased levels of IFNL2 in their sputum compared with healthy controls; asthmatic children also had increased levels of IFNL1 in their sputum." (PMID 34899712, 2021).
ZIKV infection (7 papers, 2019 to 2023). "After ZIKV infection, essential antiviral ISGs, such as IFITs and IFITMs, and essential antiviral IFNs, such as IFNL1 and IFNL3, were greatly activated in hTSCs." (PMID 37684223, 2023). "Our results indicate a possible role of IFNL1 in the control of ZIKV infection by primitive trophoblasts." (PMID 32745093, 2020). "Differently, ZIKV infection tended to up-regulate IFNL3 with FC value of 351-fold in the JEG-3 cell line but up-regulated IFNL1 with FC value of 102.6-fold in U-251 MG cells, indicating IFNL3 in the placenta may be more sensitive for antiviral effects." (PMID 36209057, 2022). "Furthermore, other interferons, such as interferon lambda 1 (IFNL1) were also over-expressed due to ZIKV infection by 48 hpi." (PMID 30984137, 2019). "Upon ZIKV infection, the expressions of IFN-related genes (such as IFNL1 and IFNL3) and ISG-related genes (such as ISG15 and ISG20) were only marginally elevated until 24 h.p.i." (PMID 36209057, 2022). "IFNL1 is a type III IFN constitutively released by primary human trophoblasts from full-term placentas, which are known to be refractory to ZIKV infection." (PMID 32745093, 2020). "During ZIKV infection we observed a reduction of IFNL1, IFIT1, and IFIT2, but not IFNB, IFIT3, and ISG15 transcription in the absence of DNA-PKcs." (PMID 36311766, 2022). "We found that although ZIKV infection induced phosphorylation of IRF3 in SC, this was dramatically diminished by R428 treatment, suggesting that IFNB1 and IFNL1 transcription in SC is responsive to ZIKV genome replication and not directly modulated by Axl-IFNAR signaling." (PMID 31311882, 2019). "Similarly, in RPE cells, where ZIKV infection does not induce IFNL1 transcription, the absence of DNA-PKcs decreased IFNB and IFIT2, but not ISG15 transcription." (PMID 36311766, 2022). "Moreover, primary human trophoblasts (PHTs) constitutively release the type III interferon-IFNL1, which may protect trophoblast and non-trophoblast cells from ZIKV infection." (PMID 36209057, 2022).
Lipedema (5 papers, 2021 to 2025). Disorder of adipose tissue characterized by symmetric and bilateral enlargement of the lower extremities due to abnormal deposition of subcutaneous fat often in obese women. "The comparison between lipedema and control patients (pre-operatively) revealed significantly increased IL-11, interferon type III family IL 29 (interferon lambda 1) and IL28A (interferon lambda 2) levels." (PMID 33805070, 2021).
chronic hepatitis C (3 papers, 2013 to 2021). "To better understand the dynamics between type I and III IFNs expression in chronic hepatitis C patients, we also quantified the expression of IFNA1, IFNL1, IFNL2, IFNL3 and IFNL4 in 24 healthy volunteers." (PMID 34307188, 2021).
autoimmune disease (2 papers, 2017 to 2023). A disorder resulting from loss of function or tissue destruction of an organ or multiple organs, arising from humoral or cellular immune responses of the individual to their own tissue constituents. "Interferon lambdas (IFN-λs; IFNL1-4) modulate immunity in the context of infections and autoimmune diseases, through a network of induced genes." (PMID 28293236, 2017).
co-infection (2 papers, 2020 to 2021). "We observed a significant upregulation of type I and III IFN (i.e., IFNB1 and IFNL1, respectively) expression at early times following IAV DIP and SARS-CoV-2 co-infection compared with SARS-CoV-2 single infection." (PMID 34359926, 2021). "To precisely define the effects of cellular co-infection on IFN induction, we measured the effects of varying bulk MOI on the induction of both type I (IFNB1) and type III (IFNL1) IFN transcription in both MDCK and A549 cells at 8 and 18 hpi under single cycle infection conditions." (PMID 33064776, 2020).
colorectal cancer (2 papers, 2024). A primary or metastatic malignant neoplasm that affects the colon or rectum. "With respect to colorectal cancer, researchers have verified that gamma irradiation directly induces type III interferon (predominantly IFNL1) expression in human colorectal cancer cell lines in a dose- and time-dependent manner." (PMID 39867908, 2024).
hepatocellular carcinoma (2 papers, 2019 to 2024). A malignant tumor that arises from hepatocytes. "NFATc3 binds to the promoter regions of IFNL1 and IFNB1 to activate their transcription in a synergistic manner with the RIG-I pathway, which can inhibit hepatitis B virus replication and hepatocellular carcinoma tumorigenesis." (PMID 39822413, 2024).
breast tumor (1 paper, 2021). "Treatment of human breast tumor suspensions with IFNL1 also induced expression of IL-12p40, a key driver of Th1 polarization." (PMID 34899712, 2021).
HCMV infection (1 paper, 2024). "Moreover, in bystander cells, IFNB1 expression was associated with viral IE gene transcription, whereas in productively infected cells expression of the highly anti-viral IFNB1, but not IFNL1, was counter-regulated upon progression of HCMV infection." (PMID 38409141, 2024). "Upon progression of HCMV infection, IFNB1 but not IFNL1 expression was inhibited, and ISG expression was shut off." (PMID 38409141, 2024).
inflammatory bowel disease (1 paper, 2025). A spectrum of small and large bowel inflammatory diseases of unknown etiology. "In this study, we have suggestive evidence for a specific role of Type III interferon signaling: inflammatory bowel disease was inversely associated with a GATE score for IFNL1, which encodes the Type III interferon IFN-λ1." (PMID 40996888, 2025). "Inflammatory bowel disease was inversely associated with GATE scores for 5 interferon-stimulated genes—IFIT1, IFI44, HERC5, MX1, IFI44L—regulated by the same trans-expression quantitative trait locus, and with the GATE score for IFNL1." (PMID 40996888, 2025).
medulloblastoma (1 paper, 2021). A malignant, invasive embryonal neoplasm arising from the cerebellum. "In addition, we found that TBEV induces also IFNL1 in human PBMC mirroring which was observed in human medulloblastoma-derived neuronal cell line (DAOY)." (PMID 33857267, 2021).
ulcer (1 paper, 2021). "Transcriptional analysis of biopsy tissue indicated that type II interferon, IFNG, not type I (IFNA4 and IFNB1) nor type III (IFNL1, IFNL2, IFNL3) interferons, was the prevalent interferon gene detected in ulcer lesions and 8 weeks post-healed skin." (PMID 34552595, 2021).